IL4 (interleukin 4)
Diseases named in the same sentence as IL4 in open-access papers (continued):
Sharing a sentence is not in itself a finding about the gene and the disease.
Cachexia (15 papers, 2009 to 2026). Severe weight loss, wasting of muscle, loss of appetite, and general debility related to a chronic disease. "Interleukin-4 (IL-4), a potent stimulator of M2-like MΦs, was shown to attenuate skeletal muscle wasting in the C26 mouse model of cachexia associated with reduced satellite cell accumulation and increased skeletal muscle CD206 protein expression." (PMID 32982782, 2020). "Thus, the role of the IL-4 in cancer associated cachexia is currently ill defined and may provide the bases for the development of new therapeutic strategies combatting both tumor and cachexia." (PMID 34408774, 2021). "Several of these upstream regulators such as IL-1 alpha, IL4, IL6, LIF, TNF have known causal roles in cachexia validated using experimental models." (PMID 33334063, 2020). "Along this line, the results of the present study show for the first time that IL4 administration to mice bearing the C26 tumour improves cachexia in terms of body weight, muscle mass, and function." (PMID 32103619, 2020). "At T1, cachexia was strongly associated with elevated GDF15 (OR 4.29; 95% CI 1.04-29.74; p = 0.044) and IL-15 (OR 43.83; 95% CI 2.39->999; p = 0.007), whereas IL-4 had a protective association (OR 0.09; 95% CI 0.00-0.66; p = 0.013)." (PMID 41749907, 2026). "Both cachexia and pre-cachexia are frequently associated with inflammation; an imbalance between pro-inflammatory (TNF-α, Interleukin (IL)-6, and IL-1) and anti-inflammatory (e.g., IL-4, IL-12, IL-15) cytokines is considered to contribute to the pathogenesis." (PMID 25988122, 2014). "In addition to IL-6, IL-4 and IL-8 also play regulatory roles in the process of cachexia." (PMID 41526343, 2026). "Therefore, although we observed decreases in IL-1α, IL-4, and IL-6 that would putatively promote an anti-inflammatory phenotype and mitigate cachexia, it is unclear whether the counter-effect of decreased IL-1RA plays a role in such discrepancies with lean body mass across studies." (PMID 36056179, 2022). "In the absence of IL-4, C57BL/6 mice exhibit severe cachexia and rapidly succumb to S. mansoni infection." (PMID 19360123, 2009).
chronic lymphocytic leukemia (15 papers, 2014 to 2024). "Other studies identified TBC1D8 as a target of IL4 in chronic lymphocytic leukemia and normal B cells." (PMID 31254352, 2019). "A study has reported that although the mRNA level of hENT1 in chronic lymphocytic leukemia cells is increased with the presence of interleukin 4 (IL-4), the hENT1-dependent uridine uptake remained unchanged." (PMID 30867652, 2019). "CD4+/PD-1+ T lymphocytes were found to be in close contact with PD-L1+ chronic lymphocytic leukemia cells and the activated PD-1/PD-L1 axis led to decreased production of IL-4 from CD4+ T lymphocytes." (PMID 30069490, 2018). "Interleukin 4 (IL-4) induces B-cell differentiation and survival of chronic lymphocytic leukemia (CLL) cells." (PMID 25909590, 2015). "Interleukin 4 (IL-4), an essential mediator of B cell development, plays a role in survival of chronic lymphocytic leukemia (CLL) cells." (PMID 25280001, 2014). "Furthermore, we found that DOCK10 levels are increased by interleukin-4 (IL-4) in B-cell lymphoid neoplasms other than chronic lymphocytic leukemia (CLL) such as mantle cell lymphoma and diffuse large B-cell lymphoma." (PMID 34449554, 2021). "In addition, apoptosis in chronic lymphocytic leukaemia (CLL) cells was prevented through Bcl-2-dependent pathways as a response to IL-4, INFα and bFGF factors." (PMID 34829672, 2021). "The IC50 reported for PF956980 against JAK3 is ~4nM, however this compound has been reported to be effective against IL-4-induced cytotoxic resistance in chronic lymphocytic leukaemia cells at concentrations of ~0.3μM in agreement with the potency of PF956980 in the present study." (PMID 26090665, 2015). "IL-4 protects chronic lymphocytic leukemia (CLL) cells from spontaneous apoptosis or killing with DNA damaging agents." (PMID 25909590, 2015). "IL-4 and IL-10 are also secreted by AML and chronic lymphocytic leukemia (CLL) cells, and these cytokines support the CLL immune escape program." (PMID 31485227, 2019). "For instance, NOTCH1 and NOTCH2 signaling are constitutively activated in chronic lymphocytic leukemia (CLL) tumors, and inhibition of NOTCH1 and NOTCH2 has been found to enhance apoptosis in CLL cells, which is accompanied by downregulation of MCL1 and upregulation of IL4." (PMID 33822486, 2021).
dementia (15 papers, 2018 to 2024). Loss of intellectual abilities interfering with an individual's social and occupational functions. "When looking at the MCI and dementia groups separately, a greater level of parkinsonism was associated with a lower level of IL-1beta and IL-4 in the MCI-LB group only." (PMID 29248892, 2018). "Moreover, other anti-inflammatory cytokines may play a protective role in dementia, such as IL-4, whose high circulating levels are associated with better cognitive function." (PMID 36613538, 2022). "T cell-mediated immunity affects the CP and attenuates the secretion of IL-4 (interleukin 4), which has been shown to be associated with brain aging and may serve as a therapeutic target for reversing or halting age-related diseases such as dementia." (PMID 35715859, 2022). "The current findings, in combination with many experimental results, suggest that the deleterious actions of microglia/macrophages-derived endogenous IL-4 and/or IL-13 are possibly involved in oxidative stress-mediated neurodegenerative disease, such as dementia and AD." (PMID 31010119, 2019). "This decrease in IL-4 with dementia severity may help explain the rapid cognitive decline seen in later stages of dementia as IL-4 can protect against amyloid-beta (Aβ)-induced neuronal toxicity while inducing a microglial phenotype that favours brain homeostasis and neuronal protection and repair." (PMID 39526037, 2024). "Specifically, we found significantly higher levels of IL-10, IL-1beta, IL-4 and IL-2 in both MCI-LB and MCI-AD compared with dementia and control subjects." (PMID 29248892, 2018). "IL-4 levels are higher in the CSF of patients with AD than in those without dementia, and AD progression is inversely correlated with IL-4 levels." (PMID 38739942, 2024). "Furthermore, we analyzed the association between IgG N-glycome and markers of inflammation including anti-inflammatory (IL-4 and IL-10) as well as proinflammatory factors (CRP, TNF-α, IFN-γ, IL-1β, and IL-6), contributing to explain the role of IgG glycosylation on dementia." (PMID 33542243, 2021). "Meanwhile, we investigate the associations between IgG N-glycan profiles and inflammation factors including anti-inflammatory (IL-4 and IL-10) and proinflammatory factors [IL-1β, IL-6, CRP, TNF-α, and interferon-gamma (IFN-γ)], which may further explain the role of IgG glycosylation in dementia." (PMID 33542243, 2021).
idiopathic pulmonary fibrosis (15 papers, 2005 to 2025). Idiopathic pulmonary fibrosis (IPF) is a nonneoplastic pulmonary disease that is characterized by the formation of scar tissue within the lungs in the absence of any known cause. "Early studies have shown a reduction in IFN-γ and an increase in IL-4 levels in the bronchoalveolar lavage and serum of patients with fibrosis, previously referred to as cryptogenic fibrosing alveolitis." (PMID 40124525, 2025). "Chronic EAA may share radiologic as well as histological features of usual interstitial pneumonia and perhaps IL-4 can play a similar role in IPF and chronic EAA." (PMID 23721656, 2013).
latent infection (15 papers, 2006 to 2025). "Five of the seven SNP that were suggestively associated with the comparison between latent infections and controls were in IL4." (PMID 29059176, 2017). "While the individual associations did not remain significant after Bonferroni correction the observation that five of the sixteen SNP tested in IL4 had suggestive associations increases the probability of a genuine association with IL4 and the risk of developing a latent infection." (PMID 29059176, 2017). "In addition, previous studies have demonstrated that increased IL-4 production is associated with advanced radiological disease, cavitary disease, and progression from latent infection to active disease." (PMID 16820066, 2006). "Cytokine expression profiles (IL-2, IL-4, IL-6, and IL-10) were analyzed in the latent infection model using flow cytometry." (PMID 40388758, 2025). "To determine the relevant producers of type 2 cytokines during chronic, latent infection, we then infected Il4KN2/+ and Il13KN4/+ mice to report endogenous IL-4 and IL-13 production, respectively." (PMID 40568097, 2025). "Increased CD8+IL-4 T cells predicted progression from latent infection to active disease in 6/10 health care workers." (PMID 23527200, 2013). "In contrast, all Il4/Il13−/− mice survived the infection and had undetectable pulmonary fungal burdens at 140 dpi, suggesting that type 2 cytokines antagonize sterilizing immunity during latent infection." (PMID 40568097, 2025). "The reactivation of latent infection is related to the deregulation of specific immune responses, decreasing inflammatory cytokines such as INF-ɣ and TNF-α associated with increasing Th2 cytokines interleukin 4 (IL4) and interleukin 10 (IL10)." (PMID 28934199, 2017). "There were suggestive associations at three loci in IL6 and TNFA in the comparison between active cases and controls, one SNP in each of APOL1, MIF and IL6 in the comparison between latent infections and active cases and seven SNP in IL4, HLA-G and TNFA between latent infections and controls." (PMID 29059176, 2017). "Similarly, we have shown that ocular infection of WT mice with a recombinant virus expressing IL-4 (HSV-IL-4), which promoted macrophage responses toward M2, was more efficacious against both primary and latent infection than mice infected with a recombinant virus expressing IFNγ (HSV- IFNγ)." (PMID 34653236, 2021). "Thus assessing the dynamic IL-4 and IFN-γ profiles from endogenously activated T cells may help distinguish between disease progression, resolution and latent infection." (PMID 23826366, 2013).
Parkinson disease (15 papers, 2015 to 2026). A progressive degenerative disorder of the central nervous system characterized by loss of dopamine producing neurons in the substantia nigra and the presence of Lewy bodies in the substantia nigra and locus coeruleus. "Furthermore, greater disease severity, whether measured for cognition or parkinsonism, was associated with lower levels of IL-1beta, IL-2 and IL-4, further supporting our finding that inflammatory markers decrease with disease progression." (PMID 29248892, 2018). "A higher level of IL-4 has been reported in juvenile parkinsonism individuals as compared to controls." (PMID 35153741, 2021). "This suggest that under pathological conditions, such as neuroinflammation when reactive oxygen species are produced, IL-13 and IL-4 can participate to tissue damage and thus to Parkinson’s disease or other neurodegenerative disorders." (PMID 27304970, 2016). "In murine models of neurodegenerative Parkinson’s disease, the intrathecal graft of hDPSCs ameliorated behavioral deficits and dopaminergic (DA) neuron loss, by upregulating anti-inflammatory cytokines IL2, IL4, and TNF-β and reducing IL-1α, IL- 1β, IL6, IL8, and TNF-α pro-inflammatory ones." (PMID 33805573, 2021). "In the PD group, age-adjusted correlations confirmed IL-4 was associated with UPDRS II (r = 0.321, p = 0.047) and PDQ-39 (r = 0.418, p = 0.009), and interferon gamma (IFN-γ) was associated with Scales for Outcomes in Parkinson’s Disease-Autonomic Questionnaire (SCOPA-AUT; r = −0.564, p = 0.001)." (PMID 40672460, 2025). "Several studies have confirmed that abnormal IL-6, CRP, TNF-α, IL-4, IL-8, and TGF-β levels were associated with worse motor function assessed by the Unified Parkinson’s Disease Rating Scale (UPDRS), whereas CRP and fractalkine might be potential markers of freezing of gait (FOG)." (PMID 36739284, 2023). "In mice, IL4 and PECAM1 also cause neuroinflammation by recruiting mast cells and upregulating the release of various mediators, which may be involved in the formation of Parkinson’s disease." (PMID 33328875, 2020). "I is reported that oral treatment with escin diminished behavioural impairments, oxidative stress and inflammation in the chronic MPTP/probenecid mouse model of Parkinson’s disease (PD) by reducing the levels of TNF-α, IL-6, IL-4, IL-10, SOD and catalase." (PMID 36830684, 2023). "Vitamin D supplementation (1 μg/kg vitamin D daily by intragastric gavage for 10 days) also attenuates neuroinflammation through the up-regulation of the anti-inflammatory cytokines (IL-10, IL-4, and TGF-β) mRNA in a Parkinson’s disease animal model." (PMID 35866081, 2022). "The increase of IL4 in the brain of Meth-treated animals, regardless of SIV infection, can therefore offer an explanation for a high incidence of Parkinson’s disease among drug users." (PMID 26441851, 2015).
polyp (15 papers, 2009 to 2025). A usually exophytic mass attached to the underlying tissue by a broad base or a thin stalk. "Patients with CRSwNP, a Th2-dominant inflammatory response is commonly observed, leading to the release of pro-inflammatory cytokines such as interleukin-4 (IL-4), IL-5, and IL-13, which contribute to eosinophilic inflammation and polyp formation." (PMID 40792313, 2025). "The results showed that the levels of Th2 cytokine, including IL-4, IL-5 and IL-4, were significantly higher in polyp group than in the healthy group, while the levels of IFN-γ we're not different from each other." (PMID 28388587, 2017). "The percentage of IFN-γ+ cells amongst the IL-21+CD8+ T cells was significantly higher than the percentage of IL-17A+ and IL-4+ cells in the polyp tissues (P < 0.001)." (PMID 27468819, 2016). "Cytokines such as IL-4 and IL-13 released during immune activation may promote mucosal hyperplasia, accelerating polyp formation and recurrence." (PMID 40606441, 2025). "In addition, the number of Tregs in PBMCs is negatively correlated with Th1- and Th2-related cytokines (such as INF-γ, IL-4, and IL-5) in polyp tissues." (PMID 35378904, 2022). "The analysis of IL-4 gene expression indicated a significantly higher level of this cytokine in the polyp tissue and nasal mucosa of the patients with CRS with Ps (CRSwP), as compared to the level in the nasal mucosa from those patients with CRS without Ps (CRS) and from the control group (DSN)." (PMID 25573836, 2015). "The number of Tregs is negatively associated with Th1- and Th2-related cytokines (such as INF-γ, IL-4, and IL-5) in polyp tissues in both atopic and nonatopic patients." (PMID 35378904, 2022). "The majority of IL-21-producing CD8+ T cells from polyp tissues co-expressed IFN-γ, but not IL-17 or IL-4, indicating that Tc1 cells were the main IL-21-producing CD8+ T cell subset in polyp tissues." (PMID 27468819, 2016).
sarcoidosis (15 papers, 2005 to 2025). Sarcoidosis is a multisystemic disorder of unknown cause characterized by the formation of immune granulomas in involved organs. "Levels of Th17 (IL17-A, IL17-F) and Th2 (IL-4, IL-13) cytokines tended to be less abundant in sarcoidosis patients relative to controls." (PMID 35668129, 2022). "Many cytokines implicated in sarcoidosis including IFN-γ and IL-2 (Type 1), IL-23 (Type 3), and IL-4 and IL-13 (Type 2) signal via the JAK – signal transducer and activator of transcription (STAT) pathway." (PMID 35668129, 2022). "After BALF CD4+ lymphocytes were stimulated with ionomycin and phorbol 12-myristate acetate, there was an appreciable increase in secreted IFNγ but a decrease in IL-4 expression in sarcoidosis patients compared to controls." (PMID 26464848, 2013). "In BAL-BD and sarcoidosis patients the Th1/Th2 (IFN-γ/IL-4) ratio and IFN-γ mRNA levels were significantly elevated compared to healthy controls." (PMID 22330585, 2012). "Studying the IL-4/IL-4R axis may also be useful to discriminate HP from sarcoidosis, as IL-4R BAL levels appear to differ, but this requires further validation." (PMID 36836922, 2023). "Moreover, increased cytokine profiles have been verified by increased BALF IFNγ+/IL-4+ CD4+ T cell ratios in sarcoidosis patients." (PMID 26464848, 2013). "Detailed investigations into peripheral IL-4 levels in sarcoidosis may also further our understanding into the mechanisms of action of immunosupressent therapy in the disease." (PMID 22815689, 2012). "However, despite similar local responses at the site of disease, the systemic response varies between individuals as evidenced by significantly higher serum IL-4 levels (and the possible elevation of IL-5 and IL-13) in sarcoidosis." (PMID 22815689, 2012). "Elevated serum IL-4 in sarcoidosis suggests that the use of selective IL-4 antagonists or soluble recombinant IL-4 receptors could be investigated for their efficacy to reduce disease activity in sarcoidosis." (PMID 22815689, 2012). "STAT6 activation is an important downstream mediator of IL4/IL13 responses in these cells, supporting its role in driving alternative (M2) macrophage activation in sarcoidosis." (PMID 40521183, 2025). "Sarcoidosis patients had decreased levels of IL-1β, IL-5, IL-8, IL-12p70, TNF-α, angiogenin, C3a, C4a, RANTES, and MCP-1 and increased levels of IL-2, IL-4, IL-6, IL-13, IFN-γ, and VEGF." (PMID 40725075, 2025). "In an independent subgroup of CVID patients, sarcoidosis patients as well as healthy donors we performed an analysis by MultiPlex Bead Arrays of BAL fluids for CXCL10, IL-4, IL-10, IL-12, and IL-17." (PMID 33613543, 2020). "Vitreous levels of IL-4, IL-17A, IL-22, IL-31, and TNFα in PDR patients were also significantly higher than those of sarcoidosis patients." (PMID 26352837, 2015). "Initially, BALF concentrations of IL-4 and IL-4R-alpha were compared in chronic EAA and sarcoidosis patients." (PMID 23721656, 2013). "Under unstimulated conditions, the difference in the percentages of IL-4 and IFNγ secreting CD4+ lymphocytes in BALF and peripheral blood of sarcoidosis patients is insignificant." (PMID 26464848, 2013). "The authors showed for the first time a significantly higher percentage of IFN-γ producing CD4+ T cells together with a markedly increased ratio of IFN-γ/IL-4-producing CD4+ T cells in BALF, after PMA/ ionomycin stimulation in patients with sarcoidosis compared with normal subjects." (PMID 15978129, 2005).